PTGS2 (prostaglandin-endoperoxide synthase 2)
Diseases named in the same sentence as PTGS2 in open-access papers (continued):
Sharing a sentence is not in itself a finding about the gene and the disease.
colitis (69 papers, 2009 to 2025). Inflammation of the colon. "PTGS2/COX-2 deletion in circulating/resident myeloid cells increases susceptibility to DSS-induced colitis." (PMID 37287987, 2023). "In a recent study using DSS-induced colitis, elevated expression of the Ptgs2 gene, which encodes COX-2, was noted." (PMID 34983592, 2022). "PTGS2 is associated with maintaining mucosal integrity and healing of colitis." (PMID 36550414, 2022). "The Western blot and immunohistochemistry examination showed that HT reduced the expression of PTGS2 in the colon with colitis, which indicated that HT suppressed ferroptosis in colitis." (PMID 39064786, 2024). "We found that HT significantly lowered the colonic mRNA expression of PTGS2 in DSS-induced colitis and influenced the response to oxidative stress of the biological process." (PMID 39064786, 2024). "In detail, HT downregulated ACSL4 and PTGS2 mRNA and protein, while it upregulated Gpx4 mRNA and protein, suggesting that HT suppressed ferroptosis in colitis in vitro." (PMID 39064786, 2024). "At the level of mRNA, the relative expression of TNFα, IL1β, IL6, MMP9, and PTGS2 increased significantly in DSS-induced colitis compared with the control group." (PMID 39064786, 2024). "The pro-inflammatory enzyme PTGS2 is upregulated in the colon of patients with IBD as well as in a DSS-induced colitis model." (PMID 39458516, 2024). "Increased inflammation and markers associated with oxidative stress, such as PTGS2 and iNOS, were present in the colons of mice with DSS-induced colitis." (PMID 39458516, 2024). "PTGS2 increased significantly in the DSS-induced colitis and decreased via the supplementation of HT." (PMID 39064786, 2024). "Reduced colitis severity was also reflected in differential tissue mRNA expression: mucosal transcript levels of S100a9, Il1b and Ptgs2 were significantly reduced in DSS-induced colitis when calcineurin inhibitors were applied." (PMID 37358998, 2023). "Coincidentally, several studies have proved that PTGS2 was inhibited by beta-sitosterol, quercetin, and berberine inhibiting the expression of PTGS2 in mouse colitis, the small intestine mucosa of rats, and human endometrial cells, respectively." (PMID 32025234, 2020). "Inhibition of Ptgs2 using inhibitors has been shown to alleviate colitis." (PMID 40356657, 2025). "We first determined the influence of HT on the protein level of PTGS2 in colitis." (PMID 39064786, 2024). "Studies have shown that PTGS2 is involved in the development of colitis and CAC46." (PMID 35365737, 2022). "Thus, lack of ABCB1/MDR1-mediated signals appears to be closely intertwined with concordant suppression of the PTGS2 and EGFR signaling pathways in colitis-associated tumorigenesis, implying severe impairment of epithelial proliferation during inflammatory injury in-vivo." (PMID 28686677, 2017). "Significant upregulation of oxidative stress and inflammatory markers, including PTGS2, iNOS, and nitrated proteins, was observed in the colons of mice with DSS-induced colitis." (PMID 39458516, 2024). "mRNA levels of Ptgs1, Ptgs2, Abcc4, and Hpgd were significantly decreased in LP macrophages from Slco2a1−/− mice with DSS-induced colitis when compared with their WT counterparts." (PMID 32184453, 2020). "Notably, PTGS2, which was identified through network pharmacological analysis as a key target for ZP in DSS-induced colitis, was also confirmed by experimental evidence." (PMID 39458516, 2024). "Indeed, the levels of PTGS2, iNOS, and nitrosylated proteins (detected using an anti-3-NT antibody) were increased in the colons of mice with DSS-induced colitis compared to those in the control group." (PMID 39458516, 2024). "Moreover, we observed increased PTGS2 and decreased GPX4, which were generally used as biomarkers of ferroptosis, in the colonic IECs from experimental colitis mice, compared with the vehicle mice." (PMID 32015337, 2020).
colitis (continued). "In a DSS-induced colitis model, we observed that activation of the HMGB1/TLR4/NF-kB pathway resulted in decreased GPX4 expression, accompanied by increased mRNA levels of ferroptosis-related indicators (PTGS2, IREB2, CS, RPL8, and ATP5G3), which was further verified by cellular experiments." (PMID 40689397, 2025). "A 16-gene signature (CARD12, CCL3, CCR3, CXCL1, F5, FAM210B, GADD45A, IL18bp, IL2RA, IL5, IL8, MMP9, PTGS2, SOCS3, TLR9 and UBE2C) was identified from 30 days post-tremelimumab initiation blood that discriminated patients developing grade 0–1 from grade 2–4 diarrhea/colitis." (PMID 30227886, 2018).
osteoarthritis (67 papers, 2006 to 2026). A noninflammatory degenerative joint disease occurring chiefly in older persons, characterized by degeneration of the articular cartilage, hypertrophy of bone at the margins and changes in the synovial membrane. "Other data highlight the anti-inflammatory effects of piperine in suppressing the PTGS2 pathway in human osteoarthritis chondrocytes, brain ischemia-reperfusion-induced inflammation, and inflammation in human keratinocyte cells after UV-B irradiation." (PMID 36678600, 2023). "Overall, this method used as an inhibitor for the damage of synovial fibroblasts by PTGS2 in osteoarthritis, which is of importance for the therapy of osteoarthritis in rats." (PMID 36690996, 2023). "Amentoflavone could reduce cartilage damage and inflammation in osteoarthritis of the knee via regulating PTGS2." (PMID 40380246, 2025). "A previous study has reported that neither COX-2 inhibitors nor the genetic deficiency of Ptgs1−/− mice or Ptgs2−/− mice exhibit a chondroprotective effect in surgery-induced osteoarthritis mice." (PMID 36078169, 2022). "Ultimately, 4 hub genes (UGCG, ESYT1, PTGS2, and CERK) were identified as vital players in osteoarthritis lipid metabolism." (PMID 38637751, 2024). "After synthesizing three machine learning algorithms, Lasso regression, SVM-RFE, and random forest, four hub genes of osteoarthritis lipid metabolism were further screened: UGCG, ESYT1, PTGS2, and CERK." (PMID 38637751, 2024). "While FRZB, important in the progression of osteoarthritis, was decreased (FC = 0.26), mainly the inflammatory factors related to osteoarthritis such as IL1R (FC = 1.24), IL-1b (FC = 2.31), MMP9 and PTGS2 showed an increased expression after the intervention." (PMID 35159340, 2022). "Puerarin, ferroptosis, and osteoarthritis share four targets: PLIN2, PTGS2, VEGFA, and IL6." (PMID 37548663, 2024). "Common targets of puerarin, ferroptosis, and osteoarthritis include PLIN2, PTGS2, VEGF, and IL6." (PMID 37548663, 2024). "Regarding the anti-inflammatory effect of piperine in the literature, it was reported that this alkaloid reduced the expression of PTGS2, PGE2, and IL-1β in osteoarthritis models, reduced inflammation after UV-B irradiation, and reduced inflammation induced by cerebral ischemia-reperfusion." (PMID 36678600, 2023).
melanoma (64 papers, 2009 to 2025). A malignant, usually aggressive tumor composed of atypical, neoplastic melanocytes. "PTGS2 is frequently overexpressed in various cancers, including melanoma, and is associated with poor prognosis due to its role in promoting tumor growth, angiogenesis, and immune suppression." (PMID 39916959, 2024). "The expression of PTGS2 associated with skin aging and melanoma, which in the co-administration group was reduced and overexpressed in UVB-induced photoaging cells." (PMID 38643459, 2024). "More recently, we have demonstrated that PTGS2 may be considered an useful diagnostic tool in defining melanoma malignancy." (PMID 31920649, 2019). "In a recent report, the first study to link Tan IIA induced ferroptosis with the STAT1/PTGS2 axis in melanoma was found." (PMID 40932870, 2025). "Cluster c11 showed an increased expression of Ptgs2 (cyclooxygenase-2) and the matricellular protein Sparc, a critical tumor-derived mediator of vascular permeability during melanoma metastatic dissemination." (PMID 39457009, 2024). "Omori and colleagues found that COX2/PTGS2 was significantly upregulated in melanoma ECs compared to normal lung EC." (PMID 35130955, 2022). "Here we describe the critical role of NRF2 in melanoma dedifferentiation, PTGS2 expression and the corresponding suppression of innate immune response genes." (PMID 32978520, 2020). "Functionally, the melanoma-induced CD14+ DCs described here, express genes (such as SSP1, PTGS2, IL-6) previously associated with immunosuppressive myeloid cells and, like monocytes and macrophages, have poor T-cell stimulatory ability." (PMID 32488012, 2020). "On the other hand, the expression of miR-143-3p, a transcriptional suppressor of PTGS2, inversely correlates with human melanoma progression confirming a key role for PTGS2 in malignant melanoma." (PMID 31920649, 2019). "Our results, demonstrating that CXCL1 serum levels were significantly reduced in B16/PTGS2Δ melanoma bearing mice, are completely in line with these findings and further support the ability of PTGS2 to regulate CXCL1 secretion in melanoma." (PMID 31920649, 2019). "The only gene found to be overexpressed in C-32 melanoma sEVs compared to primary melanocytes was PTGS2/COX-2." (PMID 30870978, 2019). "Particularly, PTGS2 is frequently expressed in malignant melanomas and its expression significantly correlates with poor survival in patients." (PMID 31920649, 2019). "In the present study, analyzing different gene expression datasets, we demonstrated that PTGS2 is predominately expressed in melanoma tissue while its expression is negligible in normal skin." (PMID 31920649, 2019). "Here, we employed the CRISPR/Cas9 technology for studying the role of prostaglandin-endoperoxide synthase 2 (PTGS2) in melanoma development and progression." (PMID 31920649, 2019). "These evidence indicate that PTGS2 has great potential to use as a biomarker and target for melanoma therapy." (PMID 31920649, 2019). "Previously, we have also demonstrated that PTGS2 level correlates with invasiveness and poor prognosis in melanoma patients." (PMID 31920649, 2019). "In fact, PTGS2 is frequently expressed in malignant melanomas and its expression significantly correlated with poor survival in patients." (PMID 31920649, 2019). "In order to investigate the correlation between PTGS2 expression and human melanoma development we performed a bioinformatics analysis of available gene expression datasets." (PMID 31920649, 2019). "In addition, they found that Tan IIA stimulated the downregulation of signal transduction and transcription factor STAT1, leading to the downregulation of PTGS2 and inhibiting ferroptosis in melanoma." (PMID 40932870, 2025). "More generally, there are evidence of a role of the PTGS2/PGE2 axis in causing and promoting the development of a variety of cancers, including non-melanoma skin cancers (basal cell carcinoma and squamous cell carcinoma) and melanoma." (PMID 39560493, 2024).
melanoma (continued). "The inhibition of PTGS2 could suppress the cell proliferation and migration in malignant melanoma by overexpression of eukaryotic translation initiation factor 3 subunit B." (PMID 38643459, 2024). "Previously, it was described that type I interferon signaling, which overlaps with the innate immune response, is suppressed by PGE2 in COX-proficient melanomas, whereas the genetic ablation of Ptgs2 or Ptgs1 and -2 enables tumor recognition by the immune system." (PMID 32978520, 2020). "Indeed, genetic ablation of Ptgs2 in BrafV600E murine melanoma cells inoculated in mice was reported to stimulate the antitumor type I immunity." (PMID 33121001, 2020). "Indeed, PTGS2 silencing in human and murine melanoma cells resulted in decreased melanogenesis, as well as MITF expression." (PMID 33121001, 2020). "Both observations indicate that PTGS2 participates in the progression of melanoma." (PMID 31920649, 2019). "Collectively, these findings confirm that PTGS2 is needed to sustain melanoma progression." (PMID 31920649, 2019). "Therefore, decreased levels of miR-143-3p in primary human melanoma lesions and metastases contributes to the up-regulation and overexpression of PTGS2 in melanoma." (PMID 31920649, 2019). "Tumor infiltration by cDC1s was confirmed by distance analyses after surface reconstruction of cDC1 profiles in confocal images, which revealed that cDC1 in Ptgs1/Ptgs2−/− BRAFV600E melanomas were located further away from the tumor margin and from CD31+ blood vessels than in control tumors." (PMID 29429633, 2018). "Collectively, these findings indicate that PTGS2 could represent an ideal gene to be targeted to limit the resistance to immunotherapy as well as to enhance the effectiveness of checkpoint inhibitors in melanoma treatment." (PMID 31920649, 2019). "Tan IIA regulates the key marker of ferroptosis, PTGS2, and knocking down PTGS2 weakens Tan IIA induced ferroptosis in melanoma cells." (PMID 40932870, 2025). "We then employed immunohistochemical staining of TMA consisting of 82 melanoma tissues to analyze the relationship between ATF3 and ferroptosis indicator PTGS2, which revealed a significant positive correlation between the staining scores of them." (PMID 35738798, 2022). "Accordingly, analysis of a previously published dataset shows that PTGS2 and MITF are regulated in an inverse manner after TNFα treatment in melanoma cells." (PMID 32978520, 2020). "When analyzing publicly available RNA sequencing datasets from melanoma cell lines, we found that the knockdown of MITF leads to a profound induction of PTGS2." (PMID 32978520, 2020). "In the present study, qPCR analyses revealed a higher expression of PTGS2 or VEGFA genes in hypoxia-treated breast and melanoma cells, respectively." (PMID 30788287, 2019). "Particularly, increased expression of PG-endoperoxide synthase 2 (PTGS2) also known as cyclooxygenase-2 (COX-2), and its major metabolite PGE2 has been observed in many different types of cancer including melanoma." (PMID 31920649, 2019). "Ptgs2 knockdown by CRISPR/Cas9 significantly inhibited cell proliferation as well as migration, invasion, and colony formation of B16F10 melanoma cells." (PMID 31920649, 2019). "Mice that rejected Ptgs2−/− tumors subsequently rejected parental COX-competent NrasG12D melanoma cells, indicating the development of immunological memory and underscoring the presence of cryptic rejection antigens in parental NrasG12D melanoma cells." (PMID 26343581, 2015). "Moreover, in stage IV melanoma patients with brain metastases, CCL18, CCR1, CCR4, CD274, CSF2, EGF, and PTGS2 genes were significantly over-expressed (p < 0.001, versus patients without melanoma brain metastasis)." (PMID 37091783, 2023). "Therefore, modulating PTGS2 expression in melanoma cells, perhaps by using genetic engineering like CRISPR technology, could be transformative to improve success rates in the development of new and highly selective drugs for melanoma treatment." (PMID 31920649, 2019).
diabetes (62 papers, 2007 to 2026). "PTGS2 is associated with the largest number of diseases, including adenocarcinoma, diabetes mellitus, fever and 108 others." (PMID 37701374, 2023). "It is traditionally believed that PTGS2, as an important mediator of inflammatory injury in diseases, produces prostaglandins (PGs) that are related to pathologic renal hemodynamics in diabetes and mediate renal injury caused by hemodynamic changes." (PMID 36482994, 2022). "Berberine reduces proteinuria and kidney damage caused by diabetes and hypertension through two key targets, PTGS2 and NOS2, which improve podocyte injury." (PMID 32025234, 2020). "Diabetes is related to the upregulation of cyclooxygenase-2 (COX2) encoded by the prostaglandin-endoperoxide synthase 2 gene (PTGS2), both in macro- and microvessels." (PMID 30151615, 2018). "The study also identifies 14 common diabetes-related targets, such as prostaglandin endoperoxide synthase 2 (PTGS2), acetylcholinesterase (ACHE), and the β2-adrenergic receptor (ADRB2)." (PMID 41356003, 2025). "The results offer us a comprehensive understanding of the therapeutic effects of previously identified target proteins, including AKT1, IL6, PPARG, JUN, CASP3, EGFR, and PTGS2, in the context of diabetes intervention." (PMID 39707185, 2024). "RELA, JUN, and PTGS2 mediate inflammatory pathways that ultimately drive insulin resistance, diabetes, and its complications." (PMID 39458839, 2024). "Among the potential targets of miR-34c-5p, some of the diabetes-related signature genes identified earlier were found, i.e. PTGS2, PDE4B and EMP1 were predicted as targets of miR-34c-5p in three to five algorithms." (PMID 26083362, 2015). "According to recent research, prostaglandin-endoperoxide synthase-2 (PTGS2), sometimes referred to as cyclo-oxygenase 2, may be involved in the etiology of type 2 diabetes mellitus (T2DM)." (PMID 40435181, 2025). "In this study, through bioinformatics analysis, we screened seven DCRGs, including PPARG, MMP9, CTNNB1, TNF, TGFB1, PTGS2, and HIF1A, and established a DCIN to comprehensively understand the diabetes-inflammation-cancer interaction." (PMID 37033970, 2023). "We identified 8 hub genes (JUN, ATF3, VEGFA, SLC2A1, HK2, PTGS2, PFKFB3, and KLF6) that were enriched in response to hypoxia, angiogenesis, vasculogenesis, hypoxia-induced signaling, cancer, diabetes, and transplant-related disease pathways." (PMID 36482897, 2022). "Moreover, increased intestinal inflammatory gene expression of TNF-α, IL-6, ICAM and PTGS-2 was found in insulin-resistant obese patients compared to non-insulin-resistant obese patients, suggesting that intestinal inflammation is involved in diabetes during obesity." (PMID 27620343, 2017). "More specifically, PTGS2 and IL1B genes were upregulated in children with diabetes." (PMID 38096208, 2023). "The results of our research suggest that EGFR, CCL2, PTGS2 and SERPINE1 proteins that play a significant role in the diabetic cardiomyopathy network may function as a druggable node to impact the repercussions of diabetes in cardiomyocytes." (PMID 40282226, 2025). "In line with the reported role of PTGS2/COX2 activation upon inflammation, sometimes beneficial/anti-inflammatory, and some others detrimental/pro-inflammatory, these results pinpointed to a controversy on the impact of PTGS2/COX2 expression in the pathogenesis of diabetes, especially in beta cells." (PMID 37705740, 2023). "On the other hand, PTGS2 gene expression was not altered in patients with diabetes." (PMID 32525457, 2020).